TMEM273 (transmembrane protein 273)
Synonyms: C10orf128; Em:AC084727.5
Tractability: Antibody: UniProt predicts a signal peptide or a membrane-spanning region.
Gene: Protein-coding gene on chromosome 10 (49,154,725 to 49,188,585, reverse strand). Ensembl gene ENSG00000204161.
Subcellular location: Membrane
Gene Ontology:
Cellular component: membrane
Genetic constraint (gnomAD): Loss-of-function variants: 20 observed, 20.27 expected, observed/expected ratio (o/e) 0.99, 90% interval 0.69 to 1.43. The upper end of that interval is the gene's LOEUF score, 1.43, which puts it in group 5 of 6, group 1 being the genes least tolerant of losing a copy. Missense variants: 194 observed, 164.81 expected, observed/expected ratio (o/e) 1.18, 90% interval 1.05 to 1.33. Synonymous variants: 66 observed, 65.65 expected, observed/expected ratio (o/e) 1.01, 90% interval 0.82 to 1.23.
Homologues: Orthologues: chimpanzee TMEM273 (93% identical), macaque TMEM273 (67% identical), mouse Tmem273 (52% identical), pig TMEM273 (51% identical), rat Tmem273 (46% identical).
Diseases named in the same sentence as TMEM273 in open-access papers:
TMEM273 is named in the same sentence as 1 disease in open-access papers, as found by Europe PMC text mining. Sharing a sentence is not in itself a finding about the gene and the disease.
TMEM273 shares sentences with these, for which no sentence is quoted: cancer (1 paper).